UBE2C (ubiquitin conjugating enzyme E2 C)
Diseases named in the same sentence as UBE2C in open-access papers (continued):
Sharing a sentence is not in itself a finding about the gene and the disease.
cancer (continued). "Lastly, we compare the gene expression of UBE2C across TCGA cancers, results revealed that the gene expression is significantly different between tumor and normal." (PMID 35812372, 2022). "In gastric cancer cells, Ube2c inhibition interrupts cell-cycle progression, while its elevation enhances cancer cell proliferation." (PMID 36499442, 2022). "When LUAD progressed to the IAC stage, RCTD data showed that UBE2C + cancer cells infiltrated the cancer region." (PMID 36434043, 2022). "IF staining showed the coexistence of Clara-like cancer cells (Epi-C1) and UBE2C + cancer cells (Epi-C6) in LUAD at three different stages, especially in AIS." (PMID 36434043, 2022). "Further, we explored the clinical value of UBE2C among 33 human cancer types, finding a consistent unfavorable prognostic impact caused by UBE2C high expression." (PMID 35332135, 2022). "By filtering the gene signature enzyme annotation in addition to ingenuity pathway analysis (IPA), the glycolysis I pathway was significantly downregulated in UBE2C‐knockdown cancer cells." (PMID 35615976, 2022). "Here, we further investigate the expression of UBE2C, its relationship with prognosis, and DNA methylation in pan-cancers." (PMID 35804892, 2022). "Consistently, UBE2C + subtype cancer cells were found to gradually and stably increase from AIS to IAC using IF and bulk RNA-seq." (PMID 36434043, 2022). "Increased UBE2C expression elevated autophagic phenotypes and drastically governed cancer cell invasive growth, EMT panels and apoptotic cell death in NSCLC, revealing the roles of motivation of autophagy genes in autophagic and apoptotic functions." (PMID 35090469, 2022). "In order to investigate the role of UBE2C in cancer tumorigenesis, we evaluated the differential expression of UBE2C between normal and cancer tissues." (PMID 35332135, 2022). "Overexpression of UBE2C has been reported in various human tumors, which leads to chromosomes mis-segregation and uncontrolled cell cycle process in cancer." (PMID 35903365, 2022). "The UBE2C gene is overexpressed in different types of cancers and considered a new target for cancers therapies." (PMID 35309509, 2022). "Still, this article did not conduct a comprehensive and intensive analysis of UBE2C, only reporting the expression of UBE2C and its relationship with cancer stage and prognosis, as well as coexpressed genes in different cancers." (PMID 35804892, 2022). "Despite the recognised importance of UBE2C in relation to cancer progression, the role played by UBE2C in BC and BC-LVI remains ill defined." (PMID 35124721, 2022). "In accordance with previous studies, a global analysis of UBE2C expression found that upregulation of UBE2C was a common feature in human cancers and predicted invasive progression." (PMID 35804892, 2022). "Using ssGSEA, we validated the effect of UBE2C + cancer cells (Epi-C6) on the prognosis of patients with LUAD in the TCGA-LUAD database and found that it can be used as a biomarker for predicting the prognosis of LUAD." (PMID 36434043, 2022). "Among 11 cancers, there were 222 genes that appeared in more than five cancer types at the same time, including UBE2C, which appeared in six types of cancer." (PMID 36292703, 2022). "Higher expression of UBE2C-u5 also indicated more advanced tumor stages and poorer prognosis across different cancer types." (PMID 36357395, 2022). "In rectal cancers, siRNA-mediated Ube2c depletion induces apoptosis and inhibits cell proliferation, further disturbing cancer growth and invasion." (PMID 36499442, 2022). "To determine the molecular mechanism of the metabolic pathway by which UBE2C regulates cancer cell progression, we downloaded GSE32873 and analysed differential gene expression between control PC3 cells and UBE2C‐knockdown PC3 cells." (PMID 35615976, 2022).
cancer (continued). "And UBE2C has been increasingly researched and recognized as an important marker overexpressed in many malignant tumors, exceeding the development as an oncogene and predicting the poor prognosis of patients." (PMID 36069832, 2022). "In summary, our study uncovered a critical role of UBE2C in regulating radiotherapy resistance to cancer." (PMID 36069832, 2022). "Taken together, these reports indicated that KAT2A, E2F1, and UBE2C play a fundamental role in the progression of several types of cancers." (PMID 36292703, 2022). "We found that the UBE2C + cancer cell subpopulation constantly increased during the invasive process of LUAD with remarkable elevation in IAC, and its spatial distribution was in the peripheral cancer region of the IAC, representing a more malignant phenotype." (PMID 36434043, 2022). "UBE2C was found to be strongly positively connected with aggressive phenotypes including nodal metastases, advanced clinical cancer stage and tumor grade by evaluating the PRCC cohort." (PMID 36385010, 2022). "To further explore the role of elevated UBE2C expression in pan-cancer tumorigenesis, we identified the top 100 genes coexpressed with UBE2C for all tumor types available in GEPIA2.0." (PMID 35804892, 2022). "UBE2C was chosen for further pan-cancer analysis on the relationship between its expression in the TCGA cohort." (PMID 35804892, 2022). "It has been found that patients with high UBE2C expression suffered a remarkably worse survival rate than those with low UBE2C expression in several human cancers." (PMID 35332135, 2022). "We first utilized the DNMIVD approach to analyze the difference in methylation of the UBE2C promoter region between tumor tissues and normal tissues for a variety of human cancers." (PMID 35804892, 2022). "The Ubiquitin-conjugating enzyme 2C (UBE2C) is essential for the ubiquitin–proteasome system and is involved in cancer cell migration and apoptosis." (PMID 35124721, 2022). "UBE2C is required for the destruction of mitotic cyclins and cell cycle progression and is involved in cancer progression." (PMID 33946279, 2021). "Studies showed that the expression levels of UBE2C were dysregulated in many cancers with unsatisfied clinical outcomes." (PMID 34950739, 2021). "Second, the potential mechanism of UBE2C promoting some cancer initiation and progression should be investigated in further study." (PMID 34950739, 2021). "By comparison, UBE2C was the only differentially expressed gene in many cancer types according to the GEPIA 2 database." (PMID 34950739, 2021). "As a conjugating enzyme, ubiquitin-conjugating enzyme 2C (UBE2C) plays an indispensable role in cancer progression." (PMID 34858987, 2021). "Emerging evidence has shown that UBE2C plays an indispensable role in ubiquitin conjugation, regulation of cell cycle progression, mitotic spindle checkpoints, and cancer progression." (PMID 34858987, 2021). "Considering the importance of the TME in the progression of cancer, our results show that UBE2C expression was markedly positively correlated with the diverse immune cell infiltration in human cancer." (PMID 34858987, 2021). "The molecular mechanism regulating the upregulation of UBE2C in different cancers is largely unresolved." (PMID 34858987, 2021). "We also performed a pan-cancer examination of the correlation between miR-140-3p and UBE2C; the results showed that miR-140-3p was negatively correlated with the expression of UBE2C in human cancer." (PMID 34858987, 2021). "TME relevance analysis indicated that UBE2C also played a crucial role in the immune response of various cancers and the results are consistent with GSEA results." (PMID 34950739, 2021). "Within community 2, we also identified increased expression of regulators of cell proliferation (CENPE, MKI67, TOP2A, UBE2C, guanine), cancer, and pluripotency (DNMT3B, DPPA4, MYC, POU5F1, CRABP2)." (PMID 33771987, 2021).
cancer (continued). "In this study, we investigated the molecular characterization and TME relevance analyses of UBE2C in more than 10,000 tumor samples of 33 cancer types." (PMID 34950739, 2021). "Of note, some earlier experiments have demonstrated that cells overexpressing UBE2C ignore the mitotic spindle checkpoint signals and lose genomic stability, which contributes to cancer progression." (PMID 33428943, 2021). "According to TMB data and the UBE2C expression level of each patient, relevance analysis in each cancer type was performed." (PMID 34950739, 2021). "In summary, our study showed that UBE2C was elevated in multiple types of human cancer and positively correlated with an unfavorable prognosis." (PMID 34858987, 2021). "Human cancer can be divided into various immunological and molecular subtypes; thus, we also examined the UBE2C expression pattern in different cancers." (PMID 34858987, 2021). "Considering that UBE2C was highly expressed in human cancer, we further explored the correlation between UBE2C expression and the pathological stages of different cancers." (PMID 34858987, 2021). "In this study, we found that UBE2C was significantly associated with the TMB and MSI in different cancers." (PMID 34858987, 2021). "The expression of NUBP2, PLCB3, PPP1CA, TBCB, and UBE2C were positively correlated with PPP1R14B in the majority of cancer types." (PMID 34858479, 2021). "We further examined the mRNA expression level of UBE2C by combining the large throughput data from the public data with our in-house RNA-seq data (a total of 628 cancer tissues and 1695 healthy control tissues)." (PMID 34488675, 2021). "In this study, we found that UBE2C was elevated in this human pan-cancer analysis, and high expression of UBE2C was correlated with poor prognosis." (PMID 34858987, 2021). "These immune markers were related to immunosuppression and regulation of antitumor activity and participated in the regulation of T cell-mediated immune response indicating that UBE2C played a vital role in the immune response in a majority of cancer types." (PMID 34950739, 2021). "GSEA was performed with the purpose of exploring the potential function of UBE2C in 33 cancer types." (PMID 34950739, 2021). "We also examined the expression of UBE2C in human cancer based on GEO data from the Oncomine database." (PMID 34858987, 2021). "Herein, we provided the first evidence to show that the METTL3/SNHG1/miR-140-3p/UBE2C axis plays a crucial role in cancer progression and the immune response in human pan-cancer." (PMID 34858987, 2021). "Suppression of MALAT1 blocked the proliferation, invasion and migration ability of cancer cells and inhibited the expression of UBE2C." (PMID 34257576, 2021). "Considering that immune cell infiltration plays an indispensable role in cancer progression, we next explored the relationship between UBE2C expression and immune cell infiltration of different cancers." (PMID 34858987, 2021). "In our study, UBE2C was identified to be differentially expressed in many cancer types and related to the initiation, progression, and prognosis of many cancers." (PMID 34950739, 2021). "We found that SNHG1 exhibited a significant negative correlation with the expression of miR-140-3p and a positive correlation with the expression of UBE2C in the pan-cancer analysis." (PMID 34858987, 2021). "The results showed that UBE2C was related to cell differentiation in a variety of cancers, such as BRCA, UCEC, KIRP, and UVM." (PMID 34950739, 2021). "Overall, these findings showed that UBE2C expression was significantly related to clinical pathological characteristics in pan-cancer types." (PMID 34858987, 2021). "In this study, we found that miR-140-3p was negatively correlated with UBE2C in a pan-cancer analysis." (PMID 34858987, 2021).
cancer (continued). "Some studies suggested UBE2C as a prognostic biomarker and potential therapeutic target in certain cancers." (PMID 34577856, 2021). "Cluster 0 and 6 were enriched in cells expressing genes related to cell cycle and cancer-associated proliferation (SFRP2, CENPF, TOP2A, UBE2C, CRABP2, MYC)." (PMID 33771987, 2021). "In our study, the higher UBE2C expression level meant a terminal clinical stage in 8 cancer types and the expression level of UBE2C was related to TMB in 20 cancer types." (PMID 34950739, 2021). "The TIMER analysis results show that UBE2C expression was significantly associated with the abundance of CD8+ T cells in 25 cancers, CD4+ T cells in 29 cancers, neutrophils in 29 cancers, DCs in 31 cancers, macrophages in 28 cancers, and B cells in 30 cancers." (PMID 34858987, 2021). "The roles of UBE2C in cell growth, invasion/migration and cancer stemness were also examined in OSCC cells." (PMID 32899896, 2020). "Increasingly studies have revealed that several genes related to cell cycle such as CDC20, TOP2A, BUBI, BUBIB, and UBE2C, are related to the occurrence and development of cancer, which were also identified in the present study." (PMID 33186389, 2020). "We selected 2 genes (UBE2C, TGFBI) with junctions that were associated with cancer and had overlap with junction data from the TCGA cohort for validation." (PMID 32437477, 2020). "The five genes (FANCB, KIF15, KIF4A, ERCC6L, and UBE2C) are all involved in fundamental cellular functions and found in many types of cancers." (PMID 32703154, 2020). "UBE2C expression is upregulated in various cancers including the liver and abnormal expression of UBE2C promotes cell cycle progression." (PMID 32703154, 2020). "Overexpression of UBE2C has been detected in many types of human cancers, and TGFBI is a candidate regulator of EMT." (PMID 32437477, 2020). "Ubiquitin-conjugating enzyme 2C (UBE2C) involves in numerous cellular processes and the tumor progression in many cancers." (PMID 32899896, 2020). "UBE2C is involved in the regulation of mitotic cyclins, cell cycle progression, and cancer progression." (PMID 31991631, 2020). "Our results indicated that knockdown of UBE2C decreased the expression levels of these cancer stemness markers including ALDH1A2, CD44, CD166 and EpCAM in both Ca9-22 and SAS cells." (PMID 32899896, 2020). "The E2 ubiquitin-conjugating enzyme family member UBE2C is overexpressed in 27 human cancers, possibly acting as a proto-oncogene." (PMID 32564237, 2020). "Studies focusing on the role of UbcH10 in cancer have been conducted on human tissues by using immunohistochemical techniques, or in tumor-derived cell lines evaluating the UBE2C mRNA expression." (PMID 32192022, 2020). "In particular, genes known to be associated with cancer such as LAMC2, UBE2C, AKT2, AKT2, BOK, MAP4, and FANCD2 were noted to be aberrantly spliced, indicating that the aberrant expression of CPSF1 significantly altered the ASEs of oncogenes in each dataset." (PMID 32437477, 2020). "UBE2C overexpression has already been reported in many cancer types, such as lung and kidney cancers." (PMID 32685988, 2020). "Because inhibiting UBE2C expression can elevate radiation and chemosensitivity and increase apoptosis, UBE2C is considered a potential therapeutic target for cancer therapy." (PMID 32397206, 2020). "In this study, the expression levels of UBE2C were evaluated in 27 different cancers using data from the Cancer Genome Atlas (TCGA) and the Genotype-Tissue Expression (GTEx) databases." (PMID 31067633, 2019). "FAM72D was reported to be a new target for cancer therapies since its expression correlates with UBE2C, whose higher expression leads to a worse OS prognosis." (PMID 31739630, 2019). "We next investigated UBE2C expression on the basis of patients’ pathological stage in TCGA cancer types." (PMID 31067633, 2019).
cancer (continued). "Those genes with strong and very strong positive correlations with UBE2C expression in all cancers are involved in the cell cycle process." (PMID 31067633, 2019). "On the other hand, Ube2c high expression has been shown to be positively correlated with unfavorable prognosis in various cancer types of: breast, bladder, lung, and thyroid gland." (PMID 30284595, 2019). "We found that UBE2C showed increased levels in all these cancers with respect to its expression in the normal tissues." (PMID 31067633, 2019). "Our results indicate that UBE2C is overexpressed in 27 studied cancers and its overexpression correlates worsen the overall survival (OS), suggesting its involvement in tumor progression and invasion." (PMID 31067633, 2019). "It is worthwhile to note that only FOXM1, E2F1, and RAD51 showed positive correlations with UBE2C in all 27 cancers." (PMID 31067633, 2019). "Genes with strong or very strong positive correlations with UBE2C expression in the 27 cancers (see Methods Section) and also some negative correlations with important tumor suppressor genes were identified in the UBE2C protein network." (PMID 31067633, 2019). "In conclusion, the current study showed that UBE2C can be considered as a general tumor marker and study of its related pathways can help to discover common therapeutic targets for cancers." (PMID 31067633, 2019). "Our results demonstrated that UBE2C is upregulated in all 27 different cancers examined and this is in agreement with previous reports showing the increased somatic expression of UBE2C in various tumor types." (PMID 31067633, 2019). "By using data available from the Cancer Genome Atlas (TCGA) and the Genotype-Tissue Expression (GTEx) databases, we here show that the ubiquitin conjugating enzyme, E2C (UBE2C), is overexpressed in all 27 cancers we investigated." (PMID 31067633, 2019). "Recently, ubiquitin-conjugating enzyme E2C (UBE2C) has been reported to be overexpressed in human cancers and act as a potential oncogene." (PMID 30914455, 2019). "We provide evidences that UBE2C acts as a proto-oncogene and can be considered as a therapeutic target for most cancers." (PMID 31067633, 2019). "Among the genes with a positive expression correlation with UBE2C, some genes that can be considered as target genes in several cancers." (PMID 31067633, 2019). "Collectively, our results indicated that deregulated UBE2C-autophagy repression axis drives NSCLC progression which renders varieties of potential molecular targets in cancer therapy of NSCLC." (PMID 29904125, 2018). "Collectively, our results indicated that deregulated UBE2C-autophagy repression axis drives NSCLC progression that renders varieties of potential molecular targets in cancer therapy of NSCLC." (PMID 29904125, 2018). "Specifically, the difference in UBE2C expression between cancer tissues and the paired normal tissues was more significant with the increased malignancy of the same type of BRCA." (PMID 29021715, 2017). "Several studies have also revealed that miRNAs interact with UBE2C to affect the progression of cancers." (PMID 29021715, 2017). "Particularly, cancers with a high degree of malignancy, low differentiation and high metastatic tendency usually present with higher UBE2C expression and poor patient survival." (PMID 29021715, 2017). "The UBE2C gene expression is low in healthy tissues, whereas it has been found abundant in several cancer tissues, including ovary, prostate, breast, thyroid, lung and uterus carcinomas." (PMID 27588470, 2016). "In this sense, it has been reported that not only the expression, but also the crucial role played by ubiquitin conjugating enzyme UBE2C in the cell cycle progression are altered in several types of cancer." (PMID 27588470, 2016). "The most significant finding in this study is the divergent mechanism of ARfl and ARv567es in regulating p-MED1 recruitment, driving p-MED1 to the UBE2C locus, and then affecting UBE2C expression and cancer cell growth." (PMID 25481872, 2015).